PAIP2B (poly(A) binding protein interacting protein 2B)
Description:
Inhibits translation of capped and polyadenylated mRNAs by displacing PABPC1 from the poly(A) tail.
Synonyms: KIAA1155
Tractability: PROTAC: UniProt records ubiquitination sites on it.
Gene: Protein-coding gene on chromosome 2 (71,182,738 to 71,227,109, reverse strand). Ensembl gene ENSG00000124374.
Subcellular location (Human Protein Atlas): Cytosol
Gene Ontology:
Molecular function: mRNA regulatory element binding translation repressor activity; protein binding; translation repressor activity
Biological process: negative regulation of translational initiation; negative regulation of translation
Cellular component: cytoplasm
Genetic constraint (gnomAD): Loss-of-function variants: 10 observed, 11.02 expected, observed/expected ratio (o/e) 0.91, 90% interval 0.56 to 1.53. The upper end of that interval is the gene's LOEUF score, 1.53, which puts it in group 6 of 6, group 1 being the genes least tolerant of losing a copy. Missense variants: 95 observed, 113.61 expected, observed/expected ratio (o/e) 0.84, 90% interval 0.71 to 0.99. Synonymous variants: 32 observed, 35.51 expected, observed/expected ratio (o/e) 0.9, 90% interval 0.68 to 1.21.
Homologues: Orthologues: chimpanzee PAIP2B (100% identical), macaque PAIP2B (100% identical), guinea pig PAIP2B (94% identical), pig PAIP2B (93% identical), rabbit PAIP2B (93% identical), mouse Paip2b (88% identical), rat Paip2b (78% identical), dog PAIP2B (65% identical), zebrafish paip2b (64% identical), Drosophila melanogaster Paip2 (26% identical). Paralogues in human: PAIP2 (61% identical).
Diseases named in the same sentence as PAIP2B in open-access papers:
PAIP2B is named in the same sentence as 5 diseases in open-access papers, as found by Europe PMC text mining. Sharing a sentence is not in itself a finding about the gene and the disease. The quoted sentences say what the papers report.
pancreatic cancer (2 papers, 2021 to 2023). "Therefore, we call for further large-sample, multiethnic pancreatic cancer patient cohort-based studies in the future, and our study will also provide a reference for further clarification of the diagnostic and prognostic value of PAIP2B in pancreatic cancer in the future." (PMID 38116489, 2023). "The aim of the study was to evaluate the potential diagnostic and prognostic value of gene, Poly A-Binding Protein Interacting Protein 2B (PAIP2B) in pancreatic cancer." (PMID 38116489, 2023). "Interestingly, we observed that there are reports of mutations and copy number variation in PAIP2B, PRDX1, RNASE1, BARD1, UHMK1, and RPL3L genes associated with pancreatic cancer." (PMID 34912796, 2021). "Most downregulated RBPs include PAIP2B, SIDT2, PDCD4, AZGP1, and RNASE1, among which we report for the first-time involvement of PAIP2B, SIDT2, PDCD4, and RNASE1 in pancreatic cancer." (PMID 34912796, 2021). "Furthermore, a total of 97 human pancreatic cancer specimens were obtained.PAIP2B-negative expression was observed in tumors examined using immunohistochemical (IHC) staining, and weakly positive expression showed in paracancerous tissue." (PMID 38116489, 2023).
melanoma (1 paper, 2014). A malignant, usually aggressive tumor composed of atypical, neoplastic melanocytes. "For other identified molecules like PAPL and PAIP2B we were unable to find a clear link to melanoma or cancer." (PMID 25437182, 2014).
tumor (2 papers, 2013 to 2023). "A total of 127 genes were upregulated upon JQ1 treatment and included those with a role in translational repression (EIF4EBP2, PAIP2B), induction of apoptosis (PPP1R13B) and tumour suppression (glucocorticosteroid (GC)-responsive gene FKBP51)." (PMID 23872705, 2013).
PAIP2B also shares sentences with these, for which no sentence is quoted: cancer (1 paper); oral cancer (1).